RPS15 (ribosomal protein S15)
Description:
Component of the small ribosomal subunit. The ribosome is a large ribonucleoprotein complex responsible for the synthesis of proteins in the cell.
Synonyms: RIG; MGC111130; S15; uS19
Tractability: Small molecule: an approved drug acts on it; a structure with a bound ligand is known; a high-quality ligand is known. PROTAC: UniProt records ubiquitination sites on it; ubiquitination databases record sites on it; its protein half-life has been measured; a small molecule that binds it is known. Other modalities: a drug acting on it is in phase 2 or 3 trials.
Target class: Other cytosolic protein
Gene: Protein-coding gene on chromosome 19 (1,438,354 to 1,440,497, forward strand). Ensembl gene ENSG00000115268.
Subcellular location: Cytoplasm
Subcellular location (Human Protein Atlas): Cytosol; Endoplasmic reticulum
Pathways (Reactome):
Metabolism of proteins: Eukaryotic Translation Termination; Formation of a pool of free 40S subunits; Formation of the ternary complex, and subsequently, the 43S complex; GTP hydrolysis and joining of the 60S ribosomal subunit; L13a-mediated translational silencing of Ceruloplasmin expression; PELO:HBS1L and ABCE1 dissociate a ribosome on a non-stop mRNA; Peptide chain elongation; Ribosomal scanning and start codon recognition; SRP-dependent cotranslational protein targeting to membrane; Translation initiation complex formation; ZNF598 and the Ribosome-associated Quality Trigger (RQT) complex dissociate a ribosome stalled on a no-go mRNA
Disease: SARS-CoV-1 modulates host translation machinery; SARS-CoV-2 modulates host translation machinery; Viral mRNA Translation
Metabolism of RNA: Major pathway of rRNA processing in the nucleolus and cytosol; Nonsense Mediated Decay (NMD) enhanced by the Exon Junction Complex (EJC); Nonsense Mediated Decay (NMD) independent of the Exon Junction Complex (EJC)
Cellular responses to stimuli: Response of EIF2AK4 (GCN2) to amino acid deficiency
Developmental Biology: Regulation of expression of SLITs and ROBOs
Metabolism: Selenocysteine synthesis
Gene Ontology:
Molecular function: MDM2/MDM4 family protein binding; protein binding; RNA binding; structural constituent of ribosome; ubiquitin ligase inhibitor activity; DNA binding
Biological process: osteoblast differentiation; ribosomal small subunit biogenesis; ribosomal small subunit export from nucleus; rRNA processing; cytoplasmic translation; translation
Cellular component: cytoplasm; cytosolic ribosome; cytosolic small ribosomal subunit; focal adhesion; membrane; cytosol; nucleoplasm; nucleus; ribosome; small ribosomal subunit
Genetic constraint (gnomAD): Loss-of-function variants: 5 observed, 10.72 expected, observed/expected ratio (o/e) 0.47, 90% interval 0.24 to 0.98. The synonymous counts are far from expectation, so gnomAD's model fits this gene poorly and the ratio says little. Missense variants: 102 observed, 161.37 expected, observed/expected ratio (o/e) 0.63, 90% interval 0.54 to 0.75. Synonymous variants: 103 observed, 70.37 expected, observed/expected ratio (o/e) 1.46, 90% interval 1.25 to 1.72.
Homologues: Orthologues: guinea pig RPS15 (100% identical), macaque RPS15 (100% identical), mouse Rps15 (100% identical), rat Rps15 (100% identical), pig RPS15 (99% identical), rabbit RPS15 (99% identical), zebrafish rps15 (97% identical), tropical clawed frog rps15 (95% identical), Drosophila melanogaster RpS15 (77% identical), Caenorhabditis elegans rps-15 (73% identical).